SERPINH1 (serpin family H member 1)
Diseases named in the same sentence as SERPINH1 in open-access papers (continued):
Sharing a sentence is not in itself a finding about the gene and the disease.
cancer (continued). "Thus, we speculate that SERPINH1 plays a key role in both carcinogenesis and cancer development." (PMID 34194496, 2021). "The expressions of five HSPs members (HSPH1, HSPD1, SERPINH1, HSPA4 and HSP90AA1) in more than 20 types of cancers were detected and compared with expressions in normal tissues using the ONCOMINE database." (PMID 32523426, 2020). "SERPINH1 and SUB1 in turn were described as oncogenes in different cancer types promoting cell proliferation and invasion." (PMID 33066457, 2020). "The findings demonstrate that SERPINH1 expression levels are significantly correlated with the prognosis of CESC patients and influence disease progression by regulating malignant phenotypes, including cancer cell proliferation, invasion, and metastasis." (PMID 40705756, 2025). "SERPINH1 supports collagen folding and ECM integrity, aiding cancer cell survival." (PMID 40959429, 2025). "Based on these results, we speculated that SERPINH1 correlates with EMT and promotes the development of cancer." (PMID 34194496, 2021). "Moreover, SERPINH1 expression was correlated with MMR, MSI, TMB, and DNA methylation in multiple types of cancer." (PMID 35058967, 2021). "Pan-cancer drug prediction analysis on the serpin superfamily was performed based on the CTRP database and the GDSC database, in which SERPINB6, SERPINE1, and SERPINH1 could predict most of the commonly used chemotherapy drugs." (PMID 37091161, 2023). "But, the relationship between SERPINH1 and immune-related therapy is not clear in pan-cancer." (PMID 36105106, 2022). "In addition, SERPINH1 was highly related to five MMR and four DNMTs genes in 7 and 22 cancers, respectively, which indicated that the mutant SERPINH1 may play a key role in the occurrence and prognosis of patients with related cancers." (PMID 35058967, 2021). "Finally, based on the results of Western blot and functional studies, we speculated that SERPINH1 may correlate with EMT and promote the development of cancer." (PMID 34194496, 2021).
infection (29 papers, 2008 to 2024). The state of being infected such as from the introduction of a foreign agent such as serum, vaccine, antigenic substance or organism. "CCK-8 and EdU tests demonstrated that infection with si-SERPINH1 greatly reduced the ability of U2OS and MNNG/HOS cells to proliferate." (PMID 37091161, 2023).
cardiovascular diseases (3 papers, 2021 to 2025). "While these results highlight the potential for targeting SERPINH1 to counteract the effects of various risk factors for cardiovascular diseases on endothelial cells, they also raise a number of questions." (PMID 33847560, 2021). "But is the production of SERPINH1 increased in the cardiac endothelial cells of patients with cardiovascular diseases?" (PMID 33847560, 2021).
cardiac diseases (2 papers, 2021 to 2024). "We focused in this study on Serpinh1, as it is a collagen chaperone and has been shown to contribute to tissue fibrosis, an important feature of many cardiac diseases." (PMID 33661096, 2021). "Not much is known about the role of SERPINH1 in heart disease." (PMID 33661096, 2021).
bone disorder (1 paper, 2023). "Eight AFF patients (NS2‐9) without a clinical suspicion of a monogenic bone disorder carried one or more heterozygous VUS with a CADD score ≥ 20 in P4HB, PHEX, TNFRSF11A, CREB3L1, TCIRG1, SERPINH1, LEPRE1, and PLOD2." (PMID 37076969, 2023).
neurodegenerative disease (1 paper, 2022). A disorder of the central nervous system characterized by gradual and progressive loss of neural tissue and neurologic function. "In addition, SERPINH1 expression was found to be increased in both AD and PD, indicating that its overexpression may correlate with different neurodegenerative diseases." (PMID 35416570, 2022).
SERPINH1 also shares sentences with these, for which no sentence is quoted: idiopathic pulmonary fibrosis (9 papers); mixed connective tissue disease (6); glioblastoma (5); chronic GVHD (4); collagen vascular disease (4); endocarditis (4); head and neck squamous cell carcinoma (4); Peritoneal Fibrosis (4); renal fibrosis (4); Stroke (4); thrombosis (4); atherosclerosis (3); autoimmune disease (3); colitis (3); connective tissue disorder (3); cryptogenic organizing pneumonia (3); dental caries (3); diabetes (3); esophageal squamous cell carcinoma (3); head and neck cancer (3); idiopathic interstitial pneumonia (3); lung diseases (3); osteomyelitis (3); renal cell carcinoma (3); Sjögren syndrome (3); viral infection (3); acute respiratory distress syndrome (2); Arthritis (2); bacterial disease (2); bladder cancer (2).
A further 107 diseases each share a sentence with SERPINH1 in 2 papers or fewer.